TNF (tumor necrosis factor)
Diseases named in the same sentence as TNF in open-access papers (continued):
Sharing a sentence is not in itself a finding about the gene and the disease.
inflammation (continued). "As such, TNF-α has a significant “mediator” role in progressive lung inflammation." (PMID 36348343, 2022). "Therefore, IL-6 and TNF-α are considered to be important mediators of chronic intestinal inflammation." (PMID 35321324, 2022). "Over the course of 7 days, DSS-treated TRPV1-hM4Di mice developed intestinal inflammation characterized by a slight decrease in the body weight, increase in macroscopic damages and production of pro-inflammatory cytokines TNF-α, IL1-β, and IL-6." (PMID 34954381, 2022). "Therefore, the decrease of claudin-4 in our study contributes to the disturbed sealing function in FAE after the TNF challenge, representing a weakened barrier in PPs during intestinal inflammation." (PMID 35707009, 2022). "In addition, it was confirmed in the LPS induced ALI model that it can induce the release of a series of inflammatory factors such as interleukin and tumor necrosis factor, which is a key factor in inducing lung inflammation." (PMID 36289489, 2022). "Three days of exposure to Pb induced severe lung inflammation as evidenced by (a) increased the gene expression of several inflammatory cytokines and mediators such as IL-4, IL-10, iNOS, TNF-α, and TGF-α and (b) inhibited the gene expression of anti-inflammatory markers such as IL-6 and IL-8." (PMID 35482242, 2022). "As such, we used TNF-α stimulated HUVECs as a model system for endothelial inflammation." (PMID 36364277, 2022). "Inhalation of ambient air pollution consisting of various toxic substances may induce pulmonary inflammation, and an oxidative stress response and induce the prothrombotic state through β2AR, IL-6, and the TNF-α signaling pathway." (PMID 35886623, 2022). "Aging leads to increased levels of pro-inflammatory factors (especially CRP, TNF-α, and IL-6) in the blood, thereby inducing long-term chronic inflammation and decreased immune function, which is also a major factor for the increased chronic disease risk in the elderly." (PMID 36294194, 2022). "IL-1β and TNF-α are potent inflammatory mediators with endocrine effects in chronic inflammation." (PMID 36232665, 2022). "This suggests the pivotal role of TNF-α in retinal inflammation in AMD." (PMID 35576057, 2022). "Previous studies also suggested that ADSCs can affect TNF-α in other inflammation disease models." (PMID 35871079, 2022). "Similar characteristics were unveiled in a mouse model, as Moraxella-infected mice showed augmented levels of IL-6, IL-1β, IL-17, and tumor necrosis factor α (TNF-α) in lungs, and neutralization of IL-17 and TNF-α was sufficient to accelerate airway inflammation and reduce the risk of AAD." (PMID 36060784, 2022). "SNPs in PNPLA3, TNF-α, AGTR1, IL-17A, IL-1B, PTPRD, and GATAD2A cause liver inflammation." (PMID 36000237, 2022). "Previous studies revealed that pro-inflammatory cytokines such as IL-1 and TNF-α could increase the intestinal TJ permeability, which has been postulated to be an important factor in the exacerbation of intestinal inflammation [25, -27]." (PMID 34319258, 2021). "In fact, TNF-α is a well-known inducer of acute liver inflammation." (PMID 33814981, 2021). "Aged mice were more susceptible to TNF-α-induced lung injury and non-toxic dose of POVPC when combined with TNF-α caused similar levels of lung inflammation." (PMID 34887839, 2021). "In summary, CNDs reduce TNF-α-mediated endothelial inflammation in HMEC-1 cells." (PMID 34068511, 2021). "Liver inflammation can then be further aggravated by various mediators including endotoxins, lymphotoxin, adipokines, chemokines, and cytokines such as tumor necrosis factor alpha (TNFα)." (PMID 34440652, 2021). "Moreover, we also exhibited that the PO extract (100 and 200 mg/kg, p.o.)inhibited lung inflammation by downregulating TNF-α, IL-6, IL-β, TGF-β, and PGE2 levels and upregulating the expression level of IL-10." (PMID 34381307, 2021).
inflammation (continued). "Moreover, in an lipopolysaccharide-induced systemic inflammation rat model, pre-treatment with clopidogrel significantly reduced levels of TNFα and IL-662." (PMID 34465804, 2021). "Biomarkers for vascular inflammation include a high plasma level of C-reactive protein, soluble cell-adhesion molecules, von Willebrand factor, aldosterone, and proinflammatory cytokines like interleukin-6 or tumor necrosis factor α." (PMID 32408603, 2020). "It is now generally accepted that tumor necrosis factor alpha (TNFα) is one of the key cytokines in the process of chronic joint inflammation and subsequent changes in cartilage and bone; its serum and synovial fluid levels correlate positively with disease scores in both OA and RA patients." (PMID 32426694, 2020). "SIRS may lead to an acute lung inflammation known as post-perfusion lung syndrome, in which TNF-α, IL-6, IL-8, and IL-1β have a pivotal role." (PMID 33505996, 2020). "In TNF-Tg mice, there was a large amount of synovial inflammation in the ankle joint, with the presence of a large number of TRAP-positive osteoclasts, and severe bone erosion was observed at the ankle joint, while cartilage with Alcian Blue-positive staining almost disappeared." (PMID 32116720, 2020). "Vascular inflammation is further promoted by the expression of endothelial cell adhesion molecules, which are induced by adipokines such as interleukin 32 (IL-32), visfatin, IL-1β, and the tumor necrosis factor (TNF)." (PMID 31694146, 2019). "Interestingly, macrophage-specific Dpep2 deletion robustly aggravated CVB3-induced cardiac inflammation, evidenced by augmented expression of TNF-α, IL-6, and MCP-1 in heart tissue." (PMID 30899700, 2019). "H.pylori infection leading to gastric chronic inflammation and mediation of the inflammatory cytokines such as IL-6, IL-1β, tumor necrosis factor alpha (TNF-α), and macrophages, may trigger gastric cell proliferation and carcinogenesis." (PMID 30447690, 2018). "This path represents our knowledge that calcified cartilage will result in degeneration of cartilage tissue, which will provoke synovial inflammation, and we hypothesized that synovial inflammation will result in positive regulation of TNF alpha." (PMID 29422110, 2018). "Therefore, to further evaluate the effects of the EAFPg on lung inflammation, we measured the inflammatory markers TNF-α, IL1-β, and IL-6." (PMID 29675437, 2018). "Progression of HF was correlated with the accumulation of M1 macrophage phenotype in the myocardium and increased production of M1 macrophages, associated with production of proinflammatory cytokines such as IFNγ, IL-6, and TNFα, which all lead to cardiac inflammation." (PMID 30024944, 2018). "Recently, it was reported that DT-13 inhibited the phosphorylation of Src (Tyr416) in TNF-α-induced human umbilical vein endothelial cells (HUVECs) and could be safely used as a potential drug for vascular inflammation." (PMID 28855900, 2017). "The elevated TNF-α could further recruit a large number of inflammatory cells and amplify the early stage of lung inflammation." (PMID 27354007, 2016). "Because macrophages play a role in resolution of inflammation, reduced levels of TNFα along with increased numbers of macrophages may indicate a pro-inflammatory role for TLR9 in lung inflammation induced following exposure to chicken barn air." (PMID 27375768, 2016). "These animals developed spontaneous joint inflammation and cartilage destruction and the administration of IL-33 inhibited the TNF-α-induced bone destruction via the IL-33/ST2 axis, which was confirmed using an ST2 agonist antibody that triggered the same downstream regulators." (PMID 24692848, 2014). "TNF-α accelerates chronic pancreatic inflammation by positive regulation of CCN2 expression." (PMID 24722330, 2014). "Brain inflammation hampers neurogenesis likely via microglia derived TNF-α." (PMID 24904290, 2014).
inflammation (continued). "Whether NOX1 and NOX4 are involved in the TNF-α-induced lung inflammation needs to be investigated in the future." (PMID 23671702, 2013). "Therefore, we measured cytokines (TNFα, IL-1β, IL-6) and a chemokine (KC) in whole lung homogenates as an additional readout for pulmonary inflammation." (PMID 24244609, 2013). "We also identified additional FGF23-responsive transcripts and activation of networks associated with renal damage and chronic inflammation, including lipocalin 2 (Lcn2), transforming growth factor beta (TGF-β) and tumor necrosis factor-alpha (TNF-α) signaling pathways." (PMID 22970174, 2012). "Although measurement of the levels of IL-23 protein is technically inconsistent, levels of IL-12(p40), one of two heteromers making up the IL-23 protein, were increased by E2, as were IL-6 and TNFα, also important early mediators of acute lung inflammation that induce IL-17." (PMID 21118573, 2010). "Chronic respiratory tract inflammation may lead to brain inflammation by altering levels of circulating cytokines, such as TNF-α and IL-1." (PMID 20019914, 2009). "Like other neurodegenerative diseases, TNF-α and other NF-κB-dependent gene products may be responsible for persistent NF-κB activation and sustained chronic retinal inflammation in rd mice, even as the photoreceptor cells disappeared in the advanced stage." (PMID 18552981, 2008). "It has been established that chronic intestinal inflammation is closely associated with the differentiated Th17 through the critical transcriptional factor retinoic acid receptor-related orphan receptor γt (ROR γt) and the key cytokines such as IL-17A, IL-22, and tumor necrosis factor-α (TNF-α)." (PMID 41400824, 2026). "Intestinal inflammation alters the gene expression patterns in the colon wall and we profiled by qRT-PCR the expression of three independent pro-inflammatory gene products [inducible nitric oxide synthase (iNOS), tumor necrosis factor alpha (TNFalpha) and interleukin-1beta (IL1beta)]." (PMID 40653455, 2025). "Furthermore, we showed that inhibition of TNF‐α significantly reduces the inflammatory responses in cerebral ECs, evidenced by attenuated activation of NF‐κB p65 and expression of VCAM‐1, highlighting a critical role of TNF‐α in reperfusion‐induced endothelial inflammation." (PMID 37789643, 2024). "The correlation analysis revealed that the Clostridia_UCG_014 and NK4A214_groups were significantly and positively correlated with TNF-α in the intestine, and the altered composition of this microbiota could be related to the occurrence of intestinal inflammation." (PMID 37565077, 2023). "Thus, TNF-α-stimulated HUVECs were used as a model of endothelial inflammation." (PMID 36606274, 2022). "However, etanercept (an antagonist of TNF-α) markedly reduced the levels of colonic inflammation." (PMID 35237152, 2022). "Furthermore, PFKFB3 knockdown significantly inhibited TNF-α-induced endothelial inflammation." (PMID 34021541, 2021). "Together, while there are several other inflammatory markers (i.e., MCP-1, TNF-α, etc.)that should be considered, this improved liver inflammation observed in the present study prior to bariatric surgery may be important for hepatic function and surgical outcomes." (PMID 32982777, 2020). "LVCF hypersensitivity in OVX rats exposed to IH was associated with lung inflammation as shown by the elevated infiltration of inflammatory cells (macrophages, neutrophils, and lymphocytes) in BALF, lung lipid peroxidation, and expression of inflammatory cytokines (NF-κB and TNF-α)." (PMID 30026705, 2018). "However, miR-155 mediates endothelial inflammation and decreases the expression of NFκB subunit p65 and adhesion protein in TNF-α-stimulated endothelial cells; miR-155 has also been identified to be flow sensitive in vitro and is therefore designated, among others, as mechano-miR." (PMID 28662100, 2017).
inflammation (continued). "In addition, TNF-α and IL-6 levels, indicators of lung inflammation, significantly correlated with sCD74 release (r = 0.511 and 0.585, p < 0.05), suggesting that increased sCD74 levels could partly reflect inflammation of lung injury." (PMID 27444250, 2016). "Recent report indicated that ethanol extracts of Pf significantly decreased TNFα production in BALF from LPS-induced airway inflammation and suggested that phenylpropanoids may contribute to the inhibitory activity of ethanol extracts of Pf on the lung inflammatory response." (PMID 26064160, 2015). "Because TNF, IL-6, and IL-13 are expressed by various leukocytes, we decided to investigate whether eosinophil-specific products could also drive chronic intestinal inflammation." (PMID 26200014, 2015). "Once activated, these T cells stimulate inflammatory responses by releasing pro-inflammatory cytokines such as interleukin-1 (IL-1), interleukin-6 (IL-6), and tumor necrosis factor-alpha (TNF-α), contributing to synovial inflammation and joint destruction." (PMID 40236704, 2025). "Chronic systemic inflammation in IBD, driven by cytokines such as TNF-α and IL-1β, can impair myocardial structure and function." (PMID 40710377, 2025). "HSP attenuated the inflammatory response by tumor necrosis factor α (TNF-α) together with a decrease in the nuclear factor-κB (NF-κB) pathway, indicating that it prevents MTX-induced liver inflammation." (PMID 40703754, 2025). "Compared to HFD‐fed WT mice, HFD‐fed Nod1−/− mice exhibited increased lung inflammation, as evidenced by higher neutrophil MPO expression and activity and elevated secretion of the cytokines TNF‐α, IL‐1β, and IL‐6." (PMID 40616268, 2025). "These immunological disturbances are driven by a dysregulated cytokine network, with pivotal roles played by interleukin (IL)-17, IL-23, and tumor necrosis factor-alpha (TNF-α), which perpetuate chronic inflammation and skin lesions." (PMID 40406126, 2025). "Pro-inflammatory cytokines, such as interleukin-1β (IL-1β), tumor necrosis factor-α (TNF-α), and interleukin-17 (IL-17), are elevated in OA joints, promoting cartilage degradation and chronic joint inflammation." (PMID 40703353, 2025). "In rat models of systemic inflammation, a GLP-1 RA, exendin, significantly lowered pro-inflammatory cytokine levels, including IL-1β, IL-6, TNF-α, and interferon-gamma (IFN-γ)." (PMID 40735319, 2025). "The accumulation and overactivation of these immune cells promote the production of proinflammatory cytokines, (such as tumor necrosis factor-α (TNF-α), interleukin-1β (IL-1β), and IL-6 driving cardiac inflammation and myocardial damage." (PMID 40260277, 2025). "It was found that in the CD18 hypomorphic psoriasiform mouse model, activated macrophages played a pivotal role in chronic inflammation through TNF-α release, with either macrophage depletion or TNF-α neutralization significantly ameliorated skin pathology." (PMID 41009795, 2025). "Chronic inflammation in CKM is characterized by high pro-inflammatory cytokines (e.g., IL-1β, IL-6, TNF-α), which activate NF-κB signaling." (PMID 40227756, 2025). "Specifically, we observed that miR-425a-5p overexpression effectively reduced pro-inflammatory cytokine production (IL-1β, IL-6, and TNF-α) in LPS-stimulated AC16 cardiomyocytes and ameliorated cardiac inflammation in the EAM mouse model." (PMID 40433545, 2025). "It was discovered that in mice with immunological liver inflammation treated with tea flower extract (TFE), the levels of nitric oxide (NO), tumor necrosis factor-α (TNF-α), and interleukin-1β (IL-1β) were markedly suppressed." (PMID 40154100, 2025). "A systematic review of human clinical trials carried out between 1980 and 2019 revealed that curcumin supplementation increased IL-10 levels and decreased MCP-1, TNF-α, IL-6, and CRP levels, reflecting its anti-inflammatory properties in chronic inflammation." (PMID 40420174, 2025).
inflammation (continued). "Inflammatory cytokines, such as tumor necrosis factor-alpha (TNF-α), interleukin-6 (IL-6), and IL-1β, which are elevated in chronic systemic inflammation, have been shown to promote microglial activation and shift them toward a pro-inflammatory phenotype." (PMID 40141084, 2025). "Both low or high-dose aspirin led to decreased TNF BALF levels and neutrophilic lung inflammation and pulmonary thromboxane B2 (TXB2) in human lung inflammation triggered by LPS." (PMID 39300444, 2024). "It has been found that DEP induced lung inflammation in mice, which displayed increased macrophages in BALF, an increase in the expression of IL-6, TNF-α, and NF-κB in pneumocytes, and a corresponding increase in the collagen fiber content of alveolar septa." (PMID 39324058, 2024). "Several reports suggest that IL-10 can inhibit antigen presentation and downregulate the formation and secretion of IL-1, IL-6, TNF-α, and other critical inflammatory aspects in macrophages and T cells, thus improving IBD intestinal inflammation." (PMID 38891089, 2024). "The occurrence of low-grade chronic inflammation in individuals with T2DM triggered an excessive secretion of inflammatory markers, including CRP, interleukin-6 (IL-6), TNF-α and monocyte chemokine 1(MCP-1)." (PMID 38528483, 2024). "The histology and TNF-alpha and BAX immunostaining evaluation in animals treated with FA verify the CRS type 3 development, characterized by heart inflammation and cell death induction." (PMID 37627587, 2023). "In the same experimental model of intestinal inflammation using C57BL/6 female mice, esculetin orally administered at 20 mg/Kg ameliorated intestinal injury, decreased MPO activity and IL-6 and TNF-α production, and inhibited NF-κB/MPAKs signaling pathways." (PMID 37111267, 2023). "In a carrageenan-induced paw inflammation model, the CB2 agonist GW405833 decreased serum concentrations of TNF and IL-1β." (PMID 37891972, 2023). "Proinflammatory cytokines such as IL-6, TNF-α, and MCP1 are key in the pathogenesis of intestinal inflammation." (PMID 36968461, 2023). "BLM induces pulmonary inflammation and PF within a short time, while BLM administered intratracheally up-regulates fibrotic factor levels, like IL-1β, IL-6, TNF-α, and TGF-β, etc.." (PMID 37160579, 2023). "IL-17 interacted with TNF-α, IL-1β, IFN-γ, and GM-CSF to exert synergistic activity on inducing inflammatory responses in chronic inflammation." (PMID 36728426, 2023). "IRAK1 plays a major function in mediating the release of TNF-α, MIP-2, CXCL1, and IL-17 cytokines along with the MAPK pathway in airway inflammation, which leads to alveolar wall thickening and accumulation of collagen fibers." (PMID 36678340, 2023). "Lycopene alleviated HDF-induced renal inflammation by inhibiting the TLR4/MyD88 inflammatory pathway by blocking inflammation in mice kidneys, including NF-kB, TNF-a, and IL-6." (PMID 36230117, 2022). "Previous studies have shown that PM2.5 can induce the release of various pro‐inflammatory cytokines, including TNF‐α, granulocyte‐macrophage colony‐stimulating factor (GM‐CSF), and IL‐6, from HBE cells and macrophages, leading to airway inflammation." (PMID 35312179, 2022). "Proinflammatory molecules, such as interleukins (IL-1β, IL-6 and IL-8), inducible nitric oxide synthase (iNOS) and tumor necrosis factor-alpha (TNF-α), responsible for the initiation and maintenance of chronic joint inflammation were also targeted." (PMID 35455072, 2022). "Therefore, initially we hypothesized that after the development of chronic allergic lung inflammation by long-term administration of intranasal HDM, mice would exhibit increased serum IL-6 and TNF-α concentrations, which had been observed in other systemic inflammation models." (PMID 36045388, 2022). "In the rat model, TQ was found to decrease interleukin-1β (IL-1β), IL-6, IFN-β, TNF-α and prostaglandin (PGE), which prevent pulmonary inflammation." (PMID 36558399, 2022).